FGFR4 (fibroblast growth factor receptor 4)
Diseases named in the same sentence as FGFR4 in open-access papers (continued):
Sharing a sentence is not in itself a finding about the gene and the disease.
tumor (continued). "While both U251-MG sublines were tumorigenic in all animals tested, upregulation of wild-type FGFR4-388Gly in the endogenously FGFR4low U251-MG cells resulted in significantly enhanced tumor volumes and shorter overall survival as compared to GFP-control tumor-bearing mice." (PMID 35484633, 2022). "Furthermore, FGFR4 was never detected in poorly differentiated areas while detectable with variable degree of expression in well-differentiated tumour glands." (PMID 35963908, 2022). "Thus, IL-1β restrained FGF19/FGFR4-induced MAPK phosphorylation and tumor generation." (PMID 33981224, 2021). "In HNSCC, various tumor locations among studies may explain the negative result on the prognostic value of the FGFR4 Arg388 SNP, since different anatomical locations show different clinical and molecular characteristics." (PMID 34737965, 2021). "In order to determine whether FGFR4 effectively reflected the status of the tumor immune microenvironment (TIME), the relationships between the FGFR4 and six TIICs (B cells, CD4 T cells, CD8 T cells, neutrophils, macrophages, and dendritic cells) were analyzed by TIMER online tool." (PMID 33407583, 2021). "FGFR4-Arg388 could activate ERK, c-scr and STAT3 signaling, contributing to tumor progression." (PMID 32154250, 2020). "Moreover, FGF401 inhibits tumor xenografts that express FGF19, FGFR-4, and Klotho-β19." (PMID 33235319, 2020). "Importantly, in support of our hypothesis, analysis of FGFR1 and FGFR4 protein expression of the patient tumor showed co-overexpression of FGFR1 (IHC score 120) and FGFR4 (IHC score 60)." (PMID 33092134, 2020). "Therefore, a TCGA analysis and immunohistochemistry, including tumor tissue from patients before and after neoadjuvant treatment, was performed to investigate the prognostic role of expression of FGF8, FGF18, and FGFR4 in adenocarcinomas of the esophago-gastric junction." (PMID 31527546, 2019). "When local response was assessed by the number of viable tumor cells in the surgical specimens, a significant correlation was found: moderate to high expression of FGFR4 was observed in 78.3% of the weakly or non-responsive cases, but in only 21.7% of responsive patients (p = 0.03 by χ2-test)." (PMID 27650548, 2016). "In RMS, major characteristic of tumour aggressiveness is represented by the PAX3/7-FOXO1 fusion gene, a negative prognostic factor that regulates transcription of several downstream tumour-driving genes, including c-Met, CXCR4, FGFR4, IGFR-1R and PDGFRα kinases." (PMID 26147305, 2015). "Thus, for the following statistical analyses tumours with FGFR4 expression were combined in one group, regardless of the number of positively stained cells and the staining intensity." (PMID 16721364, 2006). "Moreover, high intratumor heterogeneity inherent to HCC may explain why in various instances, the suppression of the FGF19/FGFR4 pathway did not result in an objective tumor response." (PMID 35655320, 2022). "In addition, overexpression of FGFR4-KD(K504M), despite lacking downstream signaling activation, might still deliver kinase-independent, tumor-promoting signals to GBM cells." (PMID 35484633, 2022). "However, we also found that the mRNA levels of Fgfr3 in the Renca model and Fgfr1 and Fgfr4 in the B16F10 model were significantly upregulated by chronic expression of VEGFR2-Fc, consistent with previous reports that FGFR1, 3, and 4 also play a critical role in tumor angiogenesis." (PMID 32076044, 2020). "Interestingly, the tumor was shown to overexpress FGFR1 and FGFR4 supporting our hypothesis." (PMID 33092134, 2020). "In the fusion-negative, FGFR4 V550L-mutant RMS559 model, 40% of mice achieved complete tumor remission and 70% overall survival." (PMID 41328353, 2026). "A tumor was not present in some of the tissue cores in the TMA [for FGFR2 (n = 2) and FGFR4 (n = 1)]." (PMID 41228379, 2025).
tumor (continued). "FGFR1-3 inhibition with AZD4547 showed significant anti-tumor effects in EOC models but not in cells highly expressing c-Met and FGF19/FGFR4, which can be treated with either c-Met and/or FGF19/FGFR4 inhibition in combination with AZD4547." (PMID 38273381, 2024). "It inhibits growth of HCC and gastric cancer cell lines expressing FGFR4, KLB and FGF19 with excellent selectivity over non-sensitive tumor models." (PMID 35655320, 2022). "Intracranial injection of BTL1528 GFP cells led to tumor bulk formation in 100% of cases (n = 5), while none of the BTL1528 FGFR4-KD(K504M)-implanted mice (n = 5) developed detectable tumors." (PMID 35484633, 2022). "In human colorectal tissue and tumor cells, a direct comparison of tumor cells between metastasis and non-metastasis tumors by GSVA analysis revealed that PTEN pathway, SMAD2 pathway, FGFR4 pathway, and JAK pathway were the enriched signatures in tumor cells." (PMID 34026600, 2021). "CGH/SNP-array analysis of the tumor showed that co-overexpression of FGFR1 and FGFR4 did not result from FGFR gene amplification." (PMID 33092134, 2020). "Therefore, in order to investigate the expression of FGF19, and the correlation between FGF19 and FGFR4, which is the main receptor for FGF19, 92 HCC tumor and adjacent non-tumor tissue samples were subjected to immunohistochemical analyses." (PMID 33674622, 2021). "Furthermore, microscopic ulceration of the tumours, which is a negative prognostic criteria according to the revised AJCC classification, was significantly correlated with positive expression of FGFR4 (P=0.009)." (PMID 16721364, 2006). "Interestingly, we also observed strong co-staining of FGFR4 and RAD51 in surgical specimens of patients who have not responded to neoadjuvant radiotherapy indicating that specifically those tumor cells that expressed high FGFR4 and upregulated RAD51 had survived the radiation treatment." (PMID 27650548, 2016).
cancer (195 papers, 2004 to 2026). A tumor composed of atypical neoplastic, often pleomorphic cells that invade other tissues. "Abnormal activation of the FGF19/FGFR4 pathway is closely linked to poor prognosis and increased malignancy in cancers such as HCC and HNSCC." (PMID 41328353, 2026). "The aberrations in the FGF19-FGFR4 pathway are not limited to overexpression; gene mutations within FGFR4 have also been implicated in tumorigenesis across various cancer types." (PMID 41503573, 2026). "FGFR19 binds to FGFR4 to transfer endocrine signaling, and FGF19-FGFR4 signaling is closely associated with cancer development and progression." (PMID 40994809, 2025). "The aberrant FGFR4 pathway was identified in human cancers, which can be caused by gene amplification, post-transcriptional dysregulation, mutations, or alternative splicing of the FGFR4 gene, and the overexpression of its ligands in cancer or stromal cells." (PMID 39858026, 2025). "In recent years, FGFR4 overexpression and activating mutations have been associated with numerous adult and pediatric cancers." (PMID 39576839, 2024). "It has been proposed that FGFR4 is altered in various cancers, and the associations between the FGFR4 rs1966265 and rs351855 variants and cancer have been described." (PMID 38540215, 2024). "Most likely, the imbalance of FGFR4 and cancer cell survival by the variant alleles of rs1966265 (A) and rs351855 (A) is because they are located at the target sites of cellular recognition and modulation." (PMID 38540215, 2024). "The AA genotype of the rs351855 variant, which encodes an arginine at codon 388 of the transmembrane domain of FGFR4, has been shown to increase cancer risk." (PMID 38540215, 2024). "Worthy of note, half of the patients had a germline variant of FGFR4 p.G388R c.1162G>A, a commonly occurring single-nucleotide polymorphism which has been associated with several cancers." (PMID 36983691, 2023). "Candidate gene studies have implicated rs351855 (p.G388R) in cancer susceptibility, and subsequent mechanistic studies showed a gain of function of the mutant FGFR4 by binding transducer and activator of transcription 3 (STAT3)." (PMID 36823471, 2023). "In the Catalogue Of Somatic Mutations In Cancer (COSMIC v98), FGFR4 is ranked as an oncogene in the Tier 1 Cancer Gene Census category of well-documented, relevant cancer genes." (PMID 37789421, 2023). "Here, we show that the loss of FGFR4 expression in PDAC is invariably associated with the acquisition of a more aggressive phenotype by cancer cells driven by hyperactivation of the mTORC1 pathway." (PMID 35963908, 2022). "Our RMS studies provide further rationale for treating subsets of cancer with inhibitors tailored to particular FGFR4 oncogenic mutations." (PMID 36097178, 2022). "Sensitivity analysis of FGFR4 G388R or V10I polymorphisms and the risk of cancer was performed by removing individual studies in turn." (PMID 33446698, 2021). "In subgroup analysis by ethnicity, we also found that the FGFR4 R-allele is correlated with an increased risk of cancer in individuals with Asian descent." (PMID 33446698, 2021). "The FGFR4 Gly388Arg polymorphism in the transmembrane domain of the receptor has been shown to increase genetic susceptibility to cancers." (PMID 34737965, 2021). "The mutation of FGFR4 and the resultant functional deficiencies were closely related to the sensitive phenotype for cancer immunotherapy." (PMID 33407583, 2021). "The SNPs from FGFR4 have been recognized as an essential participant in cancer occurrence and were associated with prognosis in patients." (PMID 33981224, 2021). "A combined meta and pool analysis of 9354 FGFR4 G388 allele statuses in multiple cancer types found an association between G388R homo/heterozygosity and reduced overall survival." (PMID 34068954, 2021). "In conclusion, this meta-analysis elucidated that FGFR4 Gly388Arg polymorphism was associated with worse prognosis in cancer patients." (PMID 34737965, 2021).
cancer (continued). "We performed a pooled analysis of studies that included 9416 cancer participants and 11,187 control subjects to investigate the relationship between the FGFR4 G388R variant and susceptibility to cancer." (PMID 33446698, 2021). "One FGFR4 single-nucleotide polymorphism (SNP), rs351855, has been shown to promote tumorigenesis and cancer progression in a mouse model of breast cancer." (PMID 34071523, 2021). "Dysregulation of FGFR4 had been reported in different types of cancers through different molecular mechanisms, including the FGFR4 and its ligand overexpression, FGFR4 single nucleotide polymorphisms (SNPs), as well as somatic mutations." (PMID 34400727, 2021). "In conclusion, this meta-analysis showed that the FGFR4 Gly388Arg polymorphism was significantly associated with worse prognosis in cancer patients." (PMID 34737965, 2021). "Given the physiological functions of the FGF19-FGFR4 pathway in BA synthesis, the blockade of FGF19, FGFR4, or β-klotho, as a potential strategy to reduce the risk of cancer progression, would result in hepatic deregulation of BA synthesis." (PMID 34200439, 2021). "It has been shown that FGFR4 gene mutation, overexpression, and amplification increase the incidence and development of different types of cancers including cancers of breast, liver, colon, prostate, and rhabdomyosarcoma and hepatocellular carcinoma." (PMID 34400727, 2021). "Herein, we performed this meta-analysis to evaluate the clinicopathological and prognostic impacts of the FGFR4 Gly388Arg polymorphism in patients with cancer." (PMID 34737965, 2021). "The FGFR4 gene rs351855 G>A polymorphism has been known to confer increased genetic susceptibility to cancers." (PMID 34737965, 2021). "Data were collected on 29,972 participants (13,793 cancer subjects and 16,179 controls) from 30 case–control studies on FGFR4 G388R polymorphism." (PMID 33446698, 2021). "In our analysis, all eligible studies based on inclusion criteria were included to extensively evaluate the association between FGFR4 G388R or V10I variants and the susceptibility of cancer." (PMID 33446698, 2021). "The association between FGFR4 G388R or V10I variants and the susceptibility of cancer has been evaluated previously, but the results are conflicting." (PMID 33446698, 2021). "The R-allele of the FGFR4 G388R variant is correlated with an increased risk of cancer in individuals with Asian descent." (PMID 33446698, 2021). "More recently, a pool analysis of 13,793 cancer patients found the FGFR4 G388R allele to be associated with increased susceptibility of cancer, which when stratified by cancer type was associated with increased risk of breast and prostate cancer." (PMID 34068954, 2021). "In the current meta-analysis, we evaluated the clinicopathological and prognostic significance of the FGFR4 Gly388Arg polymorphism in cancers." (PMID 34737965, 2021). "In the last decade, several meta-analyses were conducted to find that the FGFR4 Gly388Arg polymorphism was associated with increased risk of some cancers." (PMID 34737965, 2021). "Our data and findings from other investigations of solid tumors have shown that elevated FGFR4 expression, leading to activation of downstream oncogenic signaling pathways, was highly associated with cancer development." (PMID 34071523, 2021). "The association of the FGFR4 Arg388 polymorphism with the susceptibility to cancer has mainly been described in PC and BC." (PMID 34737965, 2021). "Numerous SNPs in FGFR genes, including FGFR4, have been identified as being significantly associated with cancer susceptibility and progression." (PMID 32781755, 2020). "The rs7708357 variant of FGFR4 significantly increased the risk of cancer development in dominant (OR = 1.17, 95% CI = 1.02–1.36, P=0.028, AG+AA GG) genetic model." (PMID 33017009, 2020). "We have also detected a common variant in FGFR4 (NM_213647.2:c.1162G > A:p.G388R) in 5 of the 8 patients, which is associated with cancer metastatic progression." (PMID 32552660, 2020).
cancer (continued). "The bioinformatics analysis identified two pathogenic variants in Fgfr4 and Nf1 genes, which are highly relevant for this type of cancer." (PMID 33231602, 2020). "Overall, we show for the first time that not only FGFR4 overexpression has pathological effects in diseases such as cancer and COPD, but also FGFR4 deficiency in the “healthy” adult lung can lead to airway inflammation." (PMID 32793609, 2020). "FGFR4 is highly activated in certain types of cancer and its activation is closely associated with its specific ligand, FGF19." (PMID 32154250, 2020). "For FGFR4 rs1966265 polymorphism, the findings revealed that this variant significantly reduced the risk of cancer susceptibility in recessive (OR = 0.87, 95% CI = 0.78–0.97, P=0.009, TT vs CT+CC) model." (PMID 33017009, 2020). "This meta-analysis aimed to estimate the association between FGFR4 rs351855 (Gly388Arg), rs1966265 (Val10Ile), rs7708357, rs2011077, and rs376618 polymorphisms and cancer risk." (PMID 33017009, 2020). "Several reports have examined the relationship between FGFR4 gene polymorphisms and diverse cancer types." (PMID 33017009, 2020). "The current investigation provided a source for basic medical scientist and clinician to understand the importance of FGFR4 in different types of cancers and use the results as potential biomarkers for susceptibility to cancers." (PMID 33017009, 2020). "Our current meta-analysis covers Gly388Arg rs351855 G>A and Val10Ile rs1966265 polymorphism in FGFR4 polymorphisms to cancer susceptibility and provide wider information in this important regulator of cancers (Rev 1-2)." (PMID 33017009, 2020). "The FGFR4 SNP rs351855 G/A, which causes a substitution of glycine for arginine at codon 388 (G388R), has been proven to be related to worse prognosis in many cancers." (PMID 32781755, 2020). "FGFR4 has been proven as an attracted target to develop a novel therapy for the subgroup of cancers associated with the FGF19–FGFR4 pathway." (PMID 30634399, 2019). "FGFR4 overexpression and gene alterations, including G388R single-nucleotide polymorphism, have been associated with cancer invasion, drug resistance, and poor prognosis." (PMID 30903103, 2019). "Recently, there have been several reports about the association between FGF19 and FGFR4 signaling and cancer prognosis." (PMID 29731962, 2018). "One such tyrosine kinase receptor is FGFR4, which has been associated with prognosis in several types of cancer, including lung cancer." (PMID 29402970, 2018). "A meta and pooled analyses provide evidence of a role for the FGFR4 Gly388Arg polymorphism in modulating patients’ outcome in different types of cancer, thus offering to clinicians a new marker to predict predisposition to poor survival in cancer patients." (PMID 30359238, 2018). "Our data suggest that individuals with AA genotype of the FGFR4 rs351855 G>A polymorphism are at significantly increased cancer risk compared with AG and GG genotypes." (PMID 28445975, 2017). "To systematically analyze the association between the FGFR4 gene rs351855 G>A polymorphism and cancer risk, we have performed this meta-analysis using 27 studies consisting of 8,682 cases and 9,731 controls." (PMID 28445975, 2017). "Overall, the FGFR4 rs351855 G>A polymorphism was associated with increased cancer risk under the recessive model (OR=1.19, 95% CI=1.01-1.41)." (PMID 28445975, 2017). "Only 23 articles consisting of 27 individual studies investigated the association between the FGFR4 rs351855 G>A polymorphism and cancer risk, and fit the eligibility criteria." (PMID 28445975, 2017). "Although the FGFR4 rs351855 G>A polymorphism has been implicated in cancer development, its association with cancer risk remains controversial." (PMID 28445975, 2017). "A study showed that during treatment with doxorubicin or cyclophosphamide, the aberrant expression of FGFR4 in cancer cells causes reduced apoptosis sensitivity." (PMID 29221201, 2017).